GTF2IRD2 (GTF2I repeat domain containing 2)
Synonyms: GTF2IRD2A; FLJ37938; FP630; GTF2IRD2 alpha
Tractability: PROTAC: ubiquitination databases record sites on it.
Gene: Protein-coding gene on chromosome 7 (74,796,144 to 74,851,611, reverse strand). Ensembl gene ENSG00000196275.
Subcellular location: Nucleus
Subcellular location (Human Protein Atlas): Nucleoplasm
Gene Ontology:
Molecular function: protein binding; DNA-binding transcription factor activity, RNA polymerase II-specific
Biological process: regulation of transcription by RNA polymerase II
Cellular component: nucleoplasm; nucleus
Genetic constraint (gnomAD): Loss-of-function variants: 4 observed, 10.51 expected, observed/expected ratio (o/e) 0.38, 90% interval 0.19 to 0.87. The synonymous counts are far from expectation, so gnomAD's model fits this gene poorly and the ratio says little. Missense variants: 51 observed, 165.33 expected, observed/expected ratio (o/e) 0.31, 90% interval 0.25 to 0.39. Synonymous variants: 18 observed, 64.83 expected, observed/expected ratio (o/e) 0.28, 90% interval 0.19 to 0.41.
Homologues: Orthologues: rat Gtf2ird2 (79% identical), mouse Gtf2ird2 (78% identical). Paralogues in human: GTF2IRD2B (99% identical), GTF2I (36% identical), GTF2IRD1 (20% identical), ZMYM4 (7% identical), ZMYM3 (7% identical), ZMYM2 (6% identical), THAP12 (6% identical), ZMYM1 (6% identical), ZMYM6 (5% identical), QRICH1 (5% identical), KIAA1958 (4% identical), SCAND3 (4% identical), and 6 more.
Diseases named in the same sentence as GTF2IRD2 in open-access papers:
GTF2IRD2 is named in the same sentence as 4 diseases in open-access papers, as found by Europe PMC text mining. Sharing a sentence is not in itself a finding about the gene and the disease. The quoted sentences say what the papers report.
Williams-Beuren Syndrome (2 papers, 2012 to 2014). "GTF2I codes for the transcription factor TFII-I that is highly expressed in the brain, and it belongs to a small paralogous gene family of transcriptional regulators that includes two other genes in the Williams-syndrome region, GTF2IRD1 and GTF2IRD2 that interact with one another in their effects." (PMID 25429715, 2014).
triple-negative breast carcinoma (1 paper, 2024). An invasive breast carcinoma which is negative for expression of estrogen receptor (ER), progesterone receptor (PR), and human epidermal growth factor receptor 2 (HER2). "Notably, the TRs of several genes, including SYNGR1, GTF2IRD2, and FAM120C, exhibited increased levels in the tumor samples of triple-negative breast cancer patients, whereas genes such as TVP23C, ICAM3, and RIMKLB displayed decreased TRs in triple-negative breast cancer tumor samples." (PMID 39349823, 2024).
GTF2IRD2 also shares sentences with these, for which no sentence is quoted: Cognitive impairment (2 papers); tumor (1).